CASP1 (caspase 1)
Diseases named in the same sentence as CASP1 in open-access papers (continued):
Sharing a sentence is not in itself a finding about the gene and the disease.
enterocolitis (1 paper, 2013). An inflammatory process affecting the small intestine and colon. "In addition, caspase-1 is critical for limiting mucosal inflammation, and modulating the production of several cytokines and chemokines that may play cytoprotective roles in Salmonella-induced enterocolitis." (PMID 23977202, 2013). "The relevance of caspase-1 dependent flagellin detection during Salmonella-induced enterocolitis has not been fully elucidated." (PMID 23977202, 2013).
ependymoma (1 paper, 2009). A WHO grade II, slow growing tumor of children and young adults, usually located intraventricularly. "The tumors suppressor genes RASSF1, CDKN2A, CDKN2B, p14ARF and TP73, as well as other genes potentially involved in the tumorigenesis of ependymomas, such as CASP1, MGMT, TIMP3 and THBS1 are epigenetically silenced by aberrant promoter methylation in subsets of ependymomas." (PMID 19333441, 2009).
Epiphora (1 paper, 2021). Abnormally increased lacrimation, that is, excessive tearing (watering eye). "Immunofluorescence data showed that in GC-1 cells, MEG3 overexpression significantly promoted NLRP3 and caspase-1 expression, indicating that it promoted epiphora, while silencing MEG3 significantly inhibited epiphora." (PMID 34222244, 2021).
falciparum malaria (1 paper, 2018). "Further, the beneficial effects of elevated plasma ABA on P. yoelii 17XNL infection were dependent on caspase-1 and on increased production of IgG, suggesting that elevated plasma ABA may be clinically relevant and protective in falciparum malaria." (PMID 29891920, 2018).
familial amyotrophic lateral sclerosis (1 paper, 2024). An instance of amyotrophic lateral sclerosis that is caused by an inherited modification of the individual's genome. "CASP1 has been reported to induce apoptosis in animal models of ischemic brain injury, and familial amyotrophic lateral sclerosis." (PMID 39350187, 2024).
fibroblast disorder (1 paper, 2017). "Further investigations on the mechanism underlying caspase-1-regulated pyroptosis and IL-18/IL-1β-regulated fibroblast disorder are required to elucidate the function of NLRP3 inflammasome in DCM." (PMID 28790925, 2017).
frontotemporal dementia (1 paper, 2022). Frontotemporal dementia (FTD) comprises a group of neurodegenerative disorders, characterized by progressive changes in behavior, executive dysfunction and language impairment, as a result of degeneration of the medial prefrontal and frontoinsular cortices. "Activation of NLRP3 inflammasome (as reflected by the increased level of cleaved caspase-1) and ASC speck-like aggregates were found in the hippocampus of patients with frontotemporal dementia (FTD) as well as in a mouse model of tau pathology (Tau22 mice which expressed human tau mutation for FTD)." (PMID 35693341, 2022).
fungal keratitis (1 paper, 2021). "TSLP induces caspase-1–dependent pyroptosis through activation of the NLRP3 inflammasome, suggesting that it may be a potential target for fungal keratitis." (PMID 34925047, 2021).
generalized seizures (1 paper, 2020). "The epilepsy group which presented generalized seizures also demonstrated a positive correlation between IL-1β vs. CASP1 and IL-6 vs. CASP3." (PMID 32219137, 2020). "Pearson's analysis demonstrated in the epilepsy group which presented generalized seizures (VV genotype), an interesting correlation between inflammatory and apoptotic parameters: IL-1β vs. caspase-1 (r = 0.7, p < 0.05) and IL-6 vs. caspase-3 (r = 0.6, p < 0.05)." (PMID 32219137, 2020).
Giardia infection (1 paper, 2021). "To identify the mediators leading to Giardia infection-associated GSDMD cleavage, we used N-acetylcysteine (NAC) and Ac-YVAD-CMK (AYC) to inhibit ROS generation and CASP1 activation, respectively." (PMID 34943932, 2021). "In the present study, we confirmed the involvement of A20-mediated NLRP3 deubiquitination in inflammasome activation, CASP1 and GSDMD cleavage, and IL-1β and IL-18 release during Giardia infection." (PMID 34943932, 2021).
gram-positive bacterial infections (1 paper, 2024). Infections caused by bacteria that retain the crystal violet stain (positive) when treated by the gram-staining method. "Gram-positive bacterial infections are mainly caused by the activation of Caspase-1." (PMID 38515339, 2024).
hemorrhagic cystitis (1 paper, 2016). Inflammation of the bladder resulting in bloody urine. "We found that elevated NLRP3 expression and ensuing activation of caspase 1 (cleaved caspase 1) to be associated with the model of hemorrhagic cystitis." (PMID 27995963, 2016).
hemorrhagic stroke (1 paper, 2022). A stroke caused by a bleed on the brain. "Other products, such as fibrinogen as DAMPs and thrombin as the ROS contributor, also promote caspase-1 activation in hemorrhagic stroke." (PMID 35370546, 2022). "Ischemic events can also be prevalent among hemorrhagic stroke, with a similar caspase-1 activation process." (PMID 35370546, 2022).
hepatic granuloma (1 paper, 2020). A granuloma located in the liver. "For this reason, we decided to evaluate whether other inflammasome pathway-related molecules, such as Casp-1, GSDMD, and IL-1R, played a role in the formation of hepatic granuloma." (PMID 32431709, 2020).
Hepatitis B (1 paper, 2023). "For example, for Hepatitis B, CASP1 and BAK1 are ranked 1 (best) and 10, respectively." (PMID 36791052, 2023).
herpes infections (1 paper, 2019). "NLRP3 inflammasome has also been the most reported in herpes infections, with consequent Caspase-1 and IL-1β activation." (PMID 31367214, 2019).
Hyperchloremia (1 paper, 2024). An abnormally increased chloride concentration in the blood. "We performed cell viability, cell toxicity, and nitric oxide (NO) release assays and studied the alteration in expression of caspase-1 and caspase-3 in different cell lines when exposed to hyperchloremia and hypernatremia." (PMID 38540164, 2024). "We investigated the impact of hyperchloremia and hypernatremia on cellular viability, cell cytotoxicity, caspase-1 and caspase-3 protein expressions, and nitric oxide release during OGD/R conditions." (PMID 38540164, 2024). "A significant decrease in caspase-3 and caspase-1 expression in the presence of 0.9% NaCl suggested that hyperchloremia might follow caspase-independent cell death pathways in microglial cells under OGD/R conditions." (PMID 38540164, 2024).
Hyperoxaluria (1 paper, 2021). Increased excretion of oxalates in the urine. "Hyperoxaluria-induced renal NLRP3 upregulation and increased caspase-1 activity and renal content of IL-1β in HP kidneys were reduced by TRPV1 inhibition." (PMID 34201387, 2021). "Because there were parallel changes in TRPV1, ALOX12, and NLRP3 expression as well as caspase-1 activation and IL-1β formation in HP kidneys, we examined whether inhibition of TRPV1 would ameliorate hyperoxaluria-induced renal inflammation and tubular injury." (PMID 34201387, 2021).
infectious peritonitis (1 paper, 2012). Inflammation of the peritoneum due to infection by bacteria or fungi. "Pro-IL-1β processing and secretion rather than synthesis proves to be increased in pMφ from infectious peritonitis suggesting up-regulation of caspase-1 in vivo." (PMID 22481867, 2012).
intervertebral disc degeneration (1 paper, 2021). "For instance, Morin mitigates thioredoxin-interacting protein (TXNIP)/NLRP3/Caspase-1 signaling pathway-mediated pyroptosis in nucleus pulposus cells and ameliorates intervertebral disc degeneration." (PMID 34366853, 2021).
intestinal inflammation (1 paper, 2017). "Although there are many types of inflammasomes, the NLRP3 inflammasome is the most extensively studied and the most complicated caspase-1 inductor in intestinal inflammation and colonic neoplasia." (PMID 28380426, 2017).
intracranial hemorrhage (1 paper, 2022). Bleeding within the SKULL, including hemorrhages in the brain and the three membranes of MENINGES. "In addition, in intracranial hemorrhage (ICH) mice, AC-YVAD-CMK (a selective inhibitor of caspase-1) inhibited pyroptosis and neuroinflammation by suppressing caspase-1 activation and IL-1β production, ultimately promoting the recovery of neurological function after ICH." (PMID 35722622, 2022).
invasive carcinoma (1 paper, 2007). A carcinoma that is not confined to the epithelium, and has spread to the surrounding stroma. "Preliminary microarray comparisons on DCIS and invasive carcinoma samples dissected from formalin-fixed paraffin sections showed a consistent downregulation of two previously identified FHIT-related genes, caspase 1 and BRCA1 in lesions underexpressing FHIT." (PMID 17164758, 2007).
ischemic cardiomyopathy (1 paper, 2022). Ischemic cardiomyopathy is a cardiomyopathy in which a weakness in the muscle of the heart due to inadequate oxygen delivery to the myocardium with coronary artery disease being the most common cause. "Research activity in vitro and on mouse models demonstrated that H2S inhibits caspase-1 activity and IL-1 secretion, with important suppression activity on pyroptosis in ischemic cardiomyopathy." (PMID 35743160, 2022).
juvenile myelomonocytic leukemia (1 paper, 2021). A myelodysplastic/myeloproliferative neoplasm of childhood that is characterized by proliferation principally of the granulocytic and monocytic lineages. "Supporting this, they found increased caspase-1 activation and IL-1β production in CMML, juvenile myelomonocytic leukemia (JMML) and AML patients with KRAS mutations as compared to patients without KRAS mutations." (PMID 35155452, 2021).
Kawasaki disease (1 paper, 2019). A rare inflammatory disease characterized by an acute febrile, systemic, self-limiting, medium-vessel vasculitis primarily affecting children. "Mice with Kawasaki’s disease, an inflammatory disease model, present impaired endothelium-dependent vasodilation accompanied by increased caspase-1, IL-1β, and VCAM-1 expression." (PMID 32009974, 2019).
kidney transplant (1 paper, 2019). A surgical procedure in which one or both kidneys from a donor are implanted into a recipient. "Notably, SNPs in CASP1, CRP, IL6R, MYD88, and TLR2 have not been examined for their impact on acute rejection in kidney transplant recipients." (PMID 32153387, 2019).
laryngeal carcinoma (1 paper, 2020). Carcinoma that arises from the laryngeal epithelium. "Western blot was performed to test the expression of IFI16, caspase-1 and IL-1β protein in 3 pairs of primary laryngeal carcinoma and their normal para-laryngeal tissues collected from 3 patients with laryngeal cancer after surgery." (PMID 32577124, 2020). "The correlation between IFI16 and caspase-1 expression was further analyzed via immunohistochemistry for 36 biopsy specimens of laryngeal carcinoma tissues." (PMID 32577124, 2020). "The significantly increased expression of IFI16 (2.32 ± 0.12-fold), caspase-1 (1.85 ± 0.13-fold), and IL-1β protein (1.93 ± 0.10-fold) was detected in laryngeal cancer tissues compared with that in adjacent tissues." (PMID 32577124, 2020). "It was reported for the first time in this study that IFI16 was overexpressed and positively correlated with caspase-1 in laryngeal carcinoma tissues." (PMID 32577124, 2020). "In line with this, the study firstly reported that IFI16 was correlated with caspase-1 in laryngeal cancer." (PMID 32577124, 2020).
lepromatous leprosy (1 paper, 2020). A chronic communicable infection which is a principal or polar form of leprosy. "In addition, were observed lowexpression of caspase-1, interleukin-1β, and interleukin-18 in tuberculoidand lepromatous leprosy." (PMID 32130367, 2020). "NLRP3 inflammasome’s immunohistochemical strong expression score is ahallmark of the Lepromatous Leprosy - The immunohistochemicalexpression of NLRP3, caspase-1, caspases-4/5, IL-1β, IL-6, and IL-18 between thegroups presented statistically significant differences in the scores." (PMID 32130367, 2020).
leukocytosis (1 paper, 2017). "Although signatures and cell composition from sIU and sIA patients were comparable to those of healthy controls, sAU patients displayed a proinflammatory signature enriched for IL-1β–inducible transcripts (IL1B and CASP1) and demonstrated leukocytosis, neutrophilia, and monocytosis." (PMID 28935693, 2017).
lung diseases (1 paper, 2023). "Hence, it is unclear whether caspase-1 inhibitor exhibits similar clinical benefits in patients with fibrosing lung diseases." (PMID 37958797, 2023).
Lymphadenopathy (1 paper, 2025). Enlargement (swelling) of a lymph node. "Caspase-1 inhibition significantly reduced systemic inflammation, lymphadenopathy and skin lesions in MRL-Faslpr mice." (PMID 41436137, 2025).
malnutrition (1 paper, 2022). Inadequate nutrition resulting from poor diet, malabsorption, or abnormal nutrient distribution. "Depletion of inflammatory monocytes by administration of DT to malnourished mice reduced bone marrow expression of caspase-1, and Il-1β in LPS challenged mice confirming their role in malnutrition-related inflammasome activation." (PMID 35983045, 2022).
meningitis (1 paper, 2015). A disorder characterized by acute inflammation of the meninges of the brain and/or spinal cord. "Similar to the in vitro results, S. pneumoniae induced caspase-1 activation and caspase-1-dependent cytokine maturation in the mouse meningitis model." (PMID 26683708, 2015).
meningococcal infection (1 paper, 2024). Infections with bacteria of the species neisseria meningitidis. "During meningococcal infection, caspase-1 activation could occur via the canonical pathway, following bacterial infection and release of pathogen-associated molecular patterns into the cytosol, and assembly of “inflammasome” platforms." (PMID 39376663, 2024).
metastasis (1 paper, 2026). The spread or migration of cancer cells from one part of the body (where they first appeared) to another. "Lower CASP1 expression was significantly associated with smaller tumor size (p = 0.005), whereas lower NLRP3 expression was associated with axillary lymph node metastasis (p = 0.003)." (PMID 41865075, 2026).
middle ear diseases (1 paper, 2021). "Regarding the potential role of inflammasomes in middle ear diseases, one experimental animal study revealed aberrant overexpression of NLRP3, ASC, caspase-1, and IL-1β in lipopolysaccharide-induced otitis media." (PMID 34805037, 2021).
monocytic leukemia (1 paper, 2025). "In the human monocytic leukemia cell line THP-1, used for inflammasome/pyroptosis studies, CLM increased release of IL-1β and active caspase-1 (compared with ATP) already 3 hours after activation (respectively)." (PMID 40371642, 2025).
mucositis (1 paper, 2017). Mucositis is inflammation and damage of the mucous membranes lining the mouth and other parts of the gastrointestinal (GI) tract. "Our present work also demonstrated the importance of proinflammatory cytokines processed by caspase-1 for the development of irradiation-induced mucositis." (PMID 28403142, 2017).
multiple system atrophy (1 paper, 2022). Multiple system atrophy (MSA) is a neurodegenerative disorder characterized by autonomic failure (cardiovascular and/or urinary), parkinsonism, cerebellar impairment and corticospinal signs with a median survival of 6-9 years. "The use of a promising Caspase-1 inhibitor VX-765 was shown to reduce α-synuclein aggregation in transgenic mice multiple system atrophy (MSA) model and reduce neuroinflammation in Alzheimer mice model." (PMID 36313019, 2022).
Mycoplasma pneumonia (1 paper, 2022). "One in vitro study of MGD on serum of children with Mycoplasma pneumonia also showed that MGD suppressed L-1β, IL-18, TNF-α, down-regulated NLRP3, pro-IL-1β, Caspase-1, pro-Caspase-1, and GSDMD-N in infected cultures and mitigated NLRP3 overexpression-induced pyroptosis." (PMID 36120338, 2022).
Myelodysplasia (1 paper, 2024). Clonal hematopoietic stem cell disorders characterized by dysplasia (ineffective production) in one or more hematopoietic cell lineages, leading to anemia and cytopenia. "Apart from its possible implication in the pathogenesis of myelodysplasia, pyroptosis also seems to drive the MDS phenotype, given that mRNA levels of the IL-1 family cytokines and caspase-1 are higher in lower-risk MDS compared to higher-risk MDS." (PMID 38397043, 2024).
myelofibrosis (1 paper, 2015). A partial or complete replacement of the bone marrow stroma by fibrous tissue. "Using D9 cells, we identified several genes involved in the inflammasome pathway, such as AIM2, IL1B, and CASP1, as downstream targets of JAK2V617F, which could explain the molecular mechanism behind myelofibrosis development in patients harboring the JAK2V617F mutation." (PMID 26823993, 2015).
myeloid leukemia (1 paper, 2024). A clonal proliferation of myeloid cells and their precursors in the bone marrow, peripheral blood, and spleen. "Thus, the AIM2-caspase-1 pathway drives ATRA+MRT-induced irreversible differentiation in myeloid leukemia cells." (PMID 38466568, 2024).
myopia (1 paper, 2023). "In conclusion, the intraperitoneal injection of MCC950 can attenuate the progression of myopia in FDM by downregulating the expression levels of NLRP3 and its downstream signaling pathway factors (IL-1β, IL-18, Caspase-1, and MMP-2)." (PMID 37958819, 2023).
Nance-Horan syndrome (1 paper, 2020). A syndrome characterized by the association in male patients of congenital cataracts with microcornea, dental anomalies and facial dysmorphism. "An interaction network analysis of the top 100 DM CpG sites showed five common regulator genes: nemo-like kinase (NLK), calcium/calmodulin-dependent protein kinase 1 (CAMKK1), lysophosphatidic acid receptor 2 (LPAR2), caspase 1 (CASP1), and Nance-Horan syndrome (NHS)." (PMID 32605309, 2020).
Neisseria gonorrhoeae infection (1 paper, 2021). "Furthermore, it has been reported that Neisseria gonorrhoeae infection promoted the activation and secretion of caspase-1 in human monocytes." (PMID 33678162, 2021).
Neurodegeneration (1 paper, 2022). Progressive loss of neural cells and tissue. "This does not prevent Caspase-1 to becoming target for tau related-neurodegeneration diseases therapy, because the tau pathology plays an increasingly important role in AD pathogenesis." (PMID 35172755, 2022).
neurofibroma (1 paper, 2017). An intraneural or extraneural neoplasm arising from nerve tissues and neural sheaths. "Of note, IL1B and CASP1, the proteinase necessary for cleavage and thus activation of IL1B, were also detected in neurofibroma lysates." (PMID 28256556, 2017). "Our gene expression data suggested the possibility that prolonged reduction of IFN-α/β in neurofibroma leads to the expression of IFN-γ and its target genes Csf1, Lif, Irf1, and Casp1 in SCs, possibly contributing to the recruitment and maturation of macrophages." (PMID 28256556, 2017).
neuropathy (1 paper, 2024). A disorder affecting the nervous system that manifests with pain, tingling, numbness, and/or muscle weakness. "It is worth mentioning that our conclusions are based on observations in two different animal models of Aβ-associated neuropathy (APP/PS1 and AppNL-G-F mice), and involved both microglia-selective as well as constitutive full body deletion of core inflammasome components (caspase-1 and Nlrp3)." (PMID 38352874, 2024).
ocular infection (1 paper, 2018). "We showed above that activated caspase-1 and pyroptosis were markedly enhanced in Trem2−/− corneas, and caspase-1 was involved in response to P. aeruginosa ocular infection." (PMID 29887864, 2018).
oral mucositis (1 paper, 2017). Inflammation of the mucous membranes of any of the structures in the mouth. "We recently defined the crucial role of ASC/caspase-1 activation and consequent IL-1β production in the establishment of inflammatory responses in irradiation-induced oral mucositis in rats." (PMID 28403142, 2017).